TET2 (tet methylcytosine dioxygenase 2)
Diseases named in the same sentence as TET2 in open-access papers (continued):
Sharing a sentence is not in itself a finding about the gene and the disease.
systemic mastocytosis (10 papers, 2012 to 2025). Systemic mastocytosis (SM) comprises a heterogeneous group of rare acquired and chronic hematological malignancies that are related to an abnormal proliferation of mast cells in tissue, including bone marrow, with or without skin involvement. "Other somatic gene alterations implicated in some cases of advanced systemic mastocytosis include mutations in TET2, SRSF2, ASXL1, RUNX1, CBL, JAK2, NRAS, and KRAS." (PMID 41440762, 2025). "In hematopoietic canine tumors, TET2 mutations have also been observed in canine mast cell tumors but in very low frequency (2.7%), contrary the TET2 mutations rate in human systemic mastocytosis, which are observed in 40% of the cases." (PMID 33194754, 2020). "In this study, we used a combination of in vitro and in vivo models to investigate a role for TET2 in the pathogenesis of KIT D816V-positive systemic mastocytosis." (PMID 24788138, 2014). "Interestingly, NGS analysis did not detect any mutations in all the other KIT exons analyzed nor in other genes previously reported in patients with advanced systemic mastocytosis (TET2, SRSF2, ASXL1, RUNX1, CBL, JAK2, NRAS, and KRAS)." (PMID 41440762, 2025). "This has clear implications for the prognosis of patients carrying TET2 mutations where AHN, often present in patients with aggressive forms of systemic mastocytosis, could progress from crosstalk between TET2/KITD816V mutated mast cells and myeloid progenitor cells in the BM." (PMID 35393954, 2022). "In this study they described a SNP in TET2 (rs1548483 C > T) nominally associated with BCR-ABL negative MPNs, as well as CML and systemic mastocytosis (SM)." (PMID 33271790, 2020).
lymphoid neoplasm (9 papers, 2014 to 2026). A neoplasm composed of a lymphocytic cell population which is usually malignant (clonal) by molecular genetic and/or immunophenotypic analysis. "Previous case reports have demonstrated AITL following either a myeloid or lymphoid neoplasm derived from a common TET2/DNMT3A mutated stem cell population." (PMID 38199781, 2023). "Two unique cases show parallel evolution of distinct lymphoid neoplasms from a common TET2/DNMT3A mutated haematopoietic progenitor." (PMID 35064935, 2022). "We have encountered two unique cases in which a lymphoid neoplasm was identified and shown to share the TET2 and DNMT3A mutations seen in an underlying neoplastic TFH cell proliferation/smouldering AITL in each case." (PMID 35064935, 2022). "Loss-of-function mutations of TET2 are common in both myeloid and lymphoid neoplasms and are associated with DNA hypermethylation and abnormal gene expression in hematopoietic cells." (PMID 34884997, 2021). "Supporting this association, the use of germ-free mice or antibiotic treatment inhibited the growth of Tet2-deficient myeloid and lymphoid tumor cells in vivo and decreased inflammatory TNFα signaling in Tet2 knockout mice." (PMID 34681910, 2021). "Most mutations of TET2 have been identified in myeloid disorders, but some have also recently been described in mature lymphoid neoplasms." (PMID 24693539, 2014). "However, the presence of somatic mutations of the TET2 gene in human mature lymphoid neoplasms has been recently described, whereby TET2 mutations were present in 2–12% of B-cell and 12% of T-cell neoplasms." (PMID 24693539, 2014). "Some gene mutations frequently identified in myeloid or lymphoid neoplasms have also been observed in RDD, e.g., ASXL1, TET2, and DNMT3A." (PMID 36358690, 2022). "A large cohort of 28 patients reported many mutations, which are implicated in other myeloid malignancies, e.g., TET2, MLL4, NF1, ALK, and ASXL1; many of these genes are driver mutations in different myeloid and lymphoid neoplasms." (PMID 36358690, 2022).
Alzheimer disease (8 papers, 2021 to 2024). A progressive, neurodegenerative disease characterized by loss of function and death of nerve cells in several areas of the brain leading to loss of cognitive function such as memory and language. "Contrastingly, TET2 depletion has also been associated with increased development of neuroinflammation in Alzheimer’s disease." (PMID 35386689, 2022). "The authors described an enrichment of rare variants in TET2 in the discovery set of a combined early-onset Alzheimer’s disease (EOAD) and FTD cohort, with an odds ratio (OR) of 28.9 (4.5–1200); P = 4.6 × 10−8." (PMID 34561610, 2021). "Neurodegenerative disease related studies have revealed that TET2 reduction exacerbates Alzheimer's disease amyloid burden and cognitive impairment." (PMID 38012545, 2023). "For example, Tet2 specific knockout in the hippocampus promotes microglial activation and exacerbates cognitive dysfunction in Alzheimer's disease mice." (PMID 38012545, 2023). "Recently, numerous studies have indicated the significance of TET2 proteins and 5-hmC in epigenetic regulation in neurodegenerative conditions such as Parkinson’s disease and Alzheimer’s disease." (PMID 35235761, 2022). "A mouse model for Alzheimer’s disease indicated TET2 depletion resulted in increased amyloid-β plaque accumulation, microglia overgrowth and proinflammatory cytokine accumulation (e.g., IL-6, IL-1B, and TNF-α)." (PMID 35386689, 2022). "Moreover, in mice models for neuroinflammation and in samples from Alzheimer’s disease patients, TET2 expression was also shown to be increased." (PMID 35386689, 2022). "In addition, an association between mutations in the DNA demethylase ten-eleven translocation 2 (TET2) and elevated risks for Alzheimer’s disease, frontotemporal dementia, and amyotrophic lateral sclerosis was recently reported with combined analysis OR of 2.3–3.7." (PMID 33616797, 2021). "It is important to determine whether lactobacillus inhibits senescence by decreasing DNMT1, m1A, m6A, TDP-43, GADD45, MMP-13, and ADAMTS1, and increasing TET2, 3MST, H2S and TIMPs in RED and Alzheimer’s disease." (PMID 39456478, 2024).
autoimmune disease (8 papers, 2017 to 2025). A disorder resulting from loss of function or tissue destruction of an organ or multiple organs, arising from humoral or cellular immune responses of the individual to their own tissue constituents. "TET2 deletion leads to Foxp3 hypermethylation, impairs Treg cell differentiation and function, as well as autoimmune disease." (PMID 36056390, 2022). "miR-142-3p also destabilizes Foxp3 by repressing Tet2, and deletion of miR-142-3p restores Tet2 expression and Treg persistence, resulting in less severe autoimmune disease." (PMID 36248881, 2022). "Mice with Tet1 and Tet2 deficiency exhibit CNS2 hypermethylation, impaired Treg cell differentiation and function, and a subsequently increased risk of developing autoimmune diseases." (PMID 34222235, 2021). "Various molecular abnormalities like TET2, SRSF2, ASXL1, and RAS are reported in the pathogenesis of CMML, but no such mutations have been described to explain the strong association of autoimmune diseases and severe inflammatory phenotype seen in CMML." (PMID 35281324, 2022). "We found that Tet2 levels were higher in the normal (i.e., “top”) β cells that we showed succumbed to immune killing during the progression of the autoimmune disease when compared to the hypogranular (i.e., “bottom”) cells that survived cytokine and immune cell-mediated killing." (PMID 34417463, 2021). "Therefore, immune cells and the immune response, which can be regulated by Tet2, are involved in the development of autoinflammatory diseases and autoimmune diseases." (PMID 34222235, 2021). "TET2, which was the most significantly downregulated gene, is universally considered as a tumor-suppressor gene and could modulate Th1 and Th17 cell differentiation and T-cell cytokine production in vivo in autoimmune diseases." (PMID 34615554, 2021). "Recently, the effect of Tet2, an essential TET protein, on the development of autoimmune diseases has been explored." (PMID 34222235, 2021). "Although Tet2 and Tet3 are the major TET proteins expressed in differentiated tissues and cell types, including lymph nodes and spleen, combined deletion of Tet1 and Tet2 also resulted in CNS2 hypermethylation, impaired Treg cell differentiation and function, and autoimmune disease." (PMID 28408905, 2017).
COVID-19 (8 papers, 2020 to 2025). A disease caused by infection with severe acute respiratory syndrome coronavirus 2. "Only Duployez and coworkers found a significant association between TET2 mutations and COVID-19 severity in males (OR = 3.940 (95% CI: 2.095–7.410, p < 0.001)." (PMID 36184726, 2023). "Our results show a higher rate of CH, especially TET2 mutations, in both COVID-19 patients and people from the retrospective cohort compared to data from the literature." (PMID 32708264, 2020). "Overall, mutations in DNMT3A and/or TET2 were present in 36% (44/122) of COVID-19 patients and were found in 80% (44/55) of those with CH." (PMID 32708264, 2020). "CH prevalence among age groups appeared higher in COVID-19 patients compared to patients from this cohort (10%, 21%, 37%, and 44% of patients aged <60 years, 60–70 years, 70–80 years, and >80 years, respectively), especially due to a higher rate of TET2 mutations in COVID-19 patients." (PMID 32708264, 2020). "DNMT3A and TET2 variants were the most frequent, with CHIP affecting 41% (N = 110) and 30% (N = 80) of our cohort of COVID-19 patients, respectively." (PMID 36184726, 2023). "Second, several targets used for COVID-19 treatment were also found in our results, including TET2 and neutrophil-mediated immunity pathway." (PMID 35071229, 2021). "Additionally, both TET2 and SRSF2, genes involved in pre-mRNA splicing, are associated with systemic inflammatory and autoimmune disease (SIAD), an umbrella term that includes ulcerative colitis and infectious diseases, such as COVID-19." (PMID 35228982, 2022). "Our data revealed that most DNA methylation changes in monocytes derived from severe COVID-19 patients occurred in genomic sites enriched in PU.1 binding motifs, consistent with earlier studies showing its role as a pioneer TF directly recruiting TET2 and DNMT3b." (PMID 36443794, 2022). "In addition, TET2 had a lower 5hmC level in the death group and MI patients’ group, and vitamin C restoring TET2 function could provide therapy for patients with COVID-19." (PMID 35071229, 2021). "In summary, we observed a high frequency of CHIP, mainly involving TET2 and DNMT3A genes, in a cohort of COVID-19 patients." (PMID 36184726, 2023). "Given that CHIP is driven by mutations in multiple epigenetic regulators, such as DNMT3A, TET2, and ASXL1, we hypothesized that altered chromatin activity might play a critical role in facilitating IFN-γ response gene expression in severe COVID-19." (PMID 36229591, 2022).
depression (8 papers, 2020 to 2024). "In the depression susceptible model, we found a continual decrease in the DNA modifying proteins (Dnmt3a, Tet2, and Tet3) while resilient animals display TDG returning to baseline." (PMID 37228107, 2023). "The NLRP3/IL-1β pathway of microglia in the ACC of AR mice is involved in the pathological process of anxiety and depression-like behavior, and the loss of TET2 further activates the NLRP3/IL-1β pathway of microglia in AR mice." (PMID 38012545, 2023). "Because deficiency of Tet2 causes depressive behaviors in mice, we further determined whether knockdown Nr2e3 in the hippocampus also causes depression‐like behaviors in mice." (PMID 38881534, 2024). "Of particular interest, the DNA modifying proteins Dnmt3a, Tet2, and Tet3 were found, suggesting that the loss or reduced expression of epigenetic machinery could be a key contributor to stress-induced depression." (PMID 37228107, 2023). "Ascorbic acid can also directly enhance the catalytic activity of Tet methylcytosine dioxygenase 2 (TET2) in the oxidation of 5-methylcytosine (5mC), promote the folding and/or recycling of the cofactor Fe (2+) for TET2, and improve symptoms of depression." (PMID 39703344, 2024). "In this study, we identified Nr2e3 as a novel transcriptional regulator of Tet2 expression in depression." (PMID 38881534, 2024). "This study illuminates Tet2's upstream regulatory mechanism, providing a new target for identifying early depression biomarkers and developing treatments." (PMID 38881534, 2024). "The role of ten-eleven translocation 2 (TET2) in AR-related anxiety and depression was assessed by Tet2−/− mice." (PMID 38012545, 2023). "Loss of TET2 activated the NLRP3/IL-1β pathway of microglia in AR mice, further accelerating the anxiety and depression-like behaviors." (PMID 38012545, 2023). "In the studies related to depression and depression-like behaviors, the low expression of TET2 also leads to the aggravation of disease symptoms." (PMID 38012545, 2023). "TET2 deficiency activates the NLRP3/IL-1β pathway of microglia in the ACC, promoting the pathological process of anxiety and depression-like behavior in AR." (PMID 38012545, 2023). "Tet1 knockout (KO) in mice enhances long-term depression and impairs memory extinction, whereas Tet2 KO increases neural stem cell proliferation and reduces differentiation potential." (PMID 32466098, 2020). "Our previous studies have demonstrated that conditional knockout of Tet2 in the nervous system or knockout of Tet2 specifically in the hippocampus of adult mice can induce depression‐like behaviors, suggesting that Tet2 is a key epigenetic factor mediating depression‐like behaviors in mice." (PMID 38881534, 2024). "Based on these findings, we hypothesized that Nr2e3 may be the primary regulator of Tet2 in the context of depression." (PMID 38881534, 2024). "The present study identified Nr2e3 as an essential transcription factor of Tet2, elucidated the upstream regulatory mechanism of Tet2, and clarified a new mechanism of depression by which Nr2e3 is involved in the regulation of synaptic plasticity through regulating Tet2." (PMID 38881534, 2024). "Targeting Tet2 expression in the brain could be a promising therapeutic strategy for abnormal behaviors, including depression and social defects." (PMID 38881534, 2024). "Furthermore, in our depression susceptible model where 5hmC continuously decreased along the ASDS-CSDS-LSDS continuum, the DNA modifying proteins Dnmt3a, Tet2, and Tet3 were found." (PMID 37228107, 2023). "Metformin could be effective in treating neuroinflammation by regulating microglia via TET2 up-regulation, indicating that metformin is a potential way to treat anxiety and depression-like behaviors in AR." (PMID 38012545, 2023). "Taken together, we hypothesized that anxiety and depression in AR are associated with the presence of microglia-mediated inflammation in the ACC, which is partly due to dysregulation of the TET2/NLRP3 axis in microglia." (PMID 38012545, 2023).
depression (continued). "Discussion: In summary, this study revealed that Tet2-mediated RNA 5hmC modification is involved in stress-related mRNA stability regulation and may serve as a potential therapeutic target for chronic stress-related diseases such as depression." (PMID 37091805, 2023). "To further demonstrate from the epigenetic level that the decrease of TET2 level in the ACC region of AR mice aggravates AR pathology and anxiety and depression-like behaviors, we detected the expression of 5-hmC by Dot Blot." (PMID 38012545, 2023). "Therefore, TET2 affects the activation of NLRP3/IL-1β pathway in microglia, which plays an important role in the occurrence and development of AR anxiety and depression-like behavior." (PMID 38012545, 2023). "Therefore, we hypothesized that in AR, TET2 may regulate the neuroimmune pathway by affecting the microglia in the ACC, leading to the anxiety and depression related symptoms of AR." (PMID 38012545, 2023).
VEXAS syndrome (8 papers, 2023 to 2025). An adult-onset inflammatory disease that affects only males and is caused by somatic, not germline, mutations. "In one study, DNMT3A mutation was seen in 47.4% with VEXAS syndrome: TET2 in 20.0% and ASXL2 in 13.3%." (PMID 36879894, 2023). "We and others have identified isolated CH mutations, predominantly in DNMT3A and TET2, in 50% of MDS cases with VEXAS syndrome (6 out of 12 cases in total, DNMT3A mutation in 2, TET2 mutation in 2)." (PMID 38819628, 2025). "NGS testing revealed mutations in TET2, U2AF1, and UBA1, leading to the diagnosis of low-risk MDS (IPSS-R of 2.5) and VEXAS syndrome." (PMID 38398362, 2024). "In addition, the hyperinflammatory microenvironment in VEXAS syndrome likely does positively select other somatically mutated clones: DNMT3A and TET2 clones are frequent in VEXAS18,19,20,21 as they are in other inflammatory clinical conditions." (PMID 37586319, 2023). "Whereas in VEXAS syndrome, UBA1 mutations alone are thought to drive both the inflammatory and MDS phenotypes, in UBA1‐wildtype patients with MDS/CMML, early somatic mutations in TET2/IDH1 (and/or SRSF2) are thought to contribute to the MDS/CMML and SIAD components." (PMID 39981058, 2024). "Similar patterns of co‐occurring mutations in myeloid diseases have been reported, including DNMT3A, TET2 and SF3B1 in MDS and VEXAS syndrome." (PMID 41310823, 2025). "Clinically, although CH mutations did not affect phenotypic heterogeneity or disease severity of VEXAS syndrome, presence of either DNMT3A or TET2 mutations increased the risk of mortality by 2 to 14-fold." (PMID 38819628, 2025).
acute lymphoblastic leukemia (7 papers, 2013 to 2025). Leukemia with an acute onset, characterized by the presence of lymphoblasts in the bone marrow and the peripheral blood. "In T-cell acute lymphoblastic leukemia (T-ALL), a phase I/II trial demonstrated that 5-aza combined with vitamin C significantly induced apoptosis in TET2-silenced cells by re-expressing TET2 and upregulating endogenous retroviruses (HERVs), thereby enhancing immunogenicity." (PMID 40917754, 2025). "From these data, we conclude that Tet2 is not required for the initiation of Kit D814V-driven acute lymphoblastic leukemia, but may play a role in disease progression in this model." (PMID 24788138, 2014). "Here, we report that in T cell acute lymphoblastic leukemia (T-ALL) the MYC oncogene controls the expression of TET1 and TET2 to maintain 5-methylcytosine (5mC) and 5-hydroxymethylcytosine (5hmC) patterns, which is associated with tumor cell-specific gene expression." (PMID 31266538, 2019). "To date, TET2 promoter hypermethylation had been observed for low-grade diffuse gliomas, a subset of Ph-negative MPN and pediatric acute lymphoblastic leukemia (ALL)." (PMID 25557833, 2015).
cutaneous melanoma (7 papers, 2015 to 2024). A primary melanoma arising from atypical melanocytes in the skin. "Recent studies have attempted to characterize the prevalence of somatic mutations to TET2, a key member of the TET family, in cutaneous melanomas." (PMID 26462027, 2015). "Similarly, online TCGA/GTEx database analysis revealed that TET2/3 expression was significantly lower in skin cutaneous melanoma (SKCM) patients than in normal people and that TET expression positively correlated with that of STAT1/3." (PMID 36854755, 2023). "However, this fraction is significantly less than the prevalence of dysfunctional TET2, as is indicated by the loss of 5-hmC in most, if not all, conventional primary cutaneous melanomas." (PMID 26462027, 2015). "FDX1 expression correlated negatively with that of TET2 and DNMT1 in BRCA, esophageal carcinoma (ESCA), GBM, HNSC, LIHC, LUAD, LUSC, and PCPG and correlated positively in skin cutaneous melanoma (SKCM)." (PMID 36210836, 2022).
Hypertension (7 papers, 2019 to 2026). The presence of chronic increased pressure in the systemic arterial system. "Among the CHIP subtypes, TET2-CHIP showed the clearest cerebrovascular signal, with significant associations with ischemic stroke, intracerebral hemorrhage, and hypertension." (PMID 42131836, 2026).